CSF2 (colony stimulating factor 2)
Diseases named in the same sentence as CSF2 in open-access papers (continued):
Sharing a sentence is not in itself a finding about the gene and the disease.
malaria (23 papers, 2011 to 2025). Malaria is a serious and sometimes fatal disease caused by a parasite that commonly infects a certain type of mosquito which feeds on humans. "We, therefore, investigated the impact of the CSF2 variants on malaria episodes over a follow-up period of 36 months." (PMID 35752805, 2022). "A model estimating the longitudinal risk of malaria showed decreased hazard rates among CSF2 AC haplotype carriers (P = 0.0045)." (PMID 35752805, 2022). "In order to understand the influence of CSF2 variants on susceptibility to malaria and SMA, the current study investigated the impact of two SNPs flanking the CSF2:g.-7032 G > A (rs168681:G > A) and CSF2:g.64544T > C (rs246835:T > C)." (PMID 35752805, 2022). "It will be important for future studies to establish the precise role of CSF2, and the soluble inflammatory mediator it encodes, GM-CSF, on susceptibility to malaria, and the subsequent development of severe disease once an individual becomes infected." (PMID 35752805, 2022). "After determining the impact of CSF2 variants on the rate of malaria and SMA episodes, we then determined the effect of the variants on the time between events using an ordered-events, generalized Cox proportional hazard model." (PMID 35752805, 2022). "In addition, the selected CSF2 homozygous and heterozygous variants (genotypes, haplotypes, and diplotypes) altered the incidence rate and hazard ratios to malaria and SMA over the follow-up period." (PMID 35752805, 2022). "To expand knowledge on the role of GM-CSF in malaria, we examined the impact of genetic variations around CSF2 on susceptibility to malaria and its severe disease manifestations (i.e., SMA and mortality) in children as they progressively develop immunity to clinical malaria." (PMID 35752805, 2022). "Similarly, the positional interaction of the CSF2 AC/GC diplotype was associated with decreased malaria episodes (P = 0.0015) compared to wild-type diplotype GT/GT." (PMID 35752805, 2022). "Moreover, results presented here illustrate that CSF2 genetic variants are associated with both the rate and timing of malaria and SMA episodes during the development of naturally acquired malarial immunity in children living in a high malaria transmission region." (PMID 35752805, 2022). "Increased IRR for malaria was observed in carriers of the CSF2 AT/GC diplotype (P = 0.0237), while the inheritance of the CSF2 AT haplotype increased the IRR for SMA (P = 0.0166)." (PMID 35752805, 2022). "Decreased incidence rate ratio (IRR) for malaria was conferred by inheritance of the CSF2:g.64544 TC genotype (P = 0.0277) and CSF2 AC/GC diplotype (P = 0.0015)." (PMID 35752805, 2022). "Conversely, co-inheritance of the CSF2 AT/GC diplotype increased the rate of malaria episodes (P = 0.0237)." (PMID 35752805, 2022). "A Poisson regression model estimating the rate of malaria episodes over 36 months revealed that the presence of the rs246835 TC heterozygote genotype and CSF2 AC/GC diplotype decreased the incidence of malaria, while the CSF2 AT/GC diplotype increased the incidence of malaria episodes." (PMID 35752805, 2022). "As presented above, TNF-α, CSF-2, and CXCL8 have been shown to be at increased levels during both malaria and babesiosis." (PMID 36839438, 2023). "Carriage of the CSF2 AC haplotype was also protective against malaria infections (P = 0.0045) relative to wild-type haplotype (GT), while co-inheritance of the CSF2 GC/GT diplotype showed a non-significant trend towards a lower risk of malaria (P = 0.1108) compared to wild type (GT/GT)." (PMID 35752805, 2022). "There was also a trend towards more malaria episodes in carriers of the CSF2 GC/GT diplotype, however, the trend was not significant (P = 0.0663)." (PMID 35752805, 2022).
type 1 diabetes (23 papers, 2012 to 2025). "Second, the CSF2 promoter contains the consensus STAT5-binding sequence where phosphorylated STAT5 is known to persistently transactivate CSF2 gene expression in autoimmune monocytes of type 1 diabetic patients." (PMID 37564209, 2023).
renal cell carcinoma (19 papers, 1995 to 2026). "Vascular endothelial growth factor C (VEGF-C), interleukin-4 (IL-4), colony-stimulating factor 2 (CSF2), prospero homeobox 1 (PROX1), and TEK receptor Tyrosine Kinase (TEK) is significantly associated with lymph node metastasis in renal cell carcinoma (RCC)." (PMID 38167072, 2024).
anemia (17 papers, 2014 to 2025). A reduction in the number of red blood cells, the amount of hemoglobin, and/or the volume of packed red blood cells. "Moreover in this review, CSF-2-deficient mice experimentally infected with P. chabaudi had higher peak parasitemia and mortality in comparison to wild-type-infected mice, but both groups had equivalent levels of anemia." (PMID 36839438, 2023). "However, CSF-2-deficient mice infected with P. chabaudi have been shown to have higher peak parasitemia, higher mortality, impaired splenomegaly, and a lower leukocyte count in comparison to wild-type-infected mice, despite equivalent levels of anemia in both groups." (PMID 36839438, 2023).
depression (17 papers, 2019 to 2025). "IL-17 A-induced inflammatory mediators, including IL-6, IL-1β, Ptgs2, Csf2, and Cxcl1, can cause myocardial inflammation and depression [,14], and have been associated with endotoxin-induced cardiac dysfunction and shock [14,]." (PMID 41311862, 2025).
sarcoidosis (16 papers, 2015 to 2025). Sarcoidosis is a multisystemic disorder of unknown cause characterized by the formation of immune granulomas in involved organs. "Indeed, a distinct CD4+FOXP3- cluster present exclusively in the sarcoidosis samples, with a Th1 phenotype marked by upregulation of IFNG and to a lesser degree CSF2 (GM-CSF), was identified." (PMID 35668129, 2022).
myocardial infarction (15 papers, 2012 to 2024). Gross necrosis of the myocardium, as a result of interruption of the blood supply to the area, as in coronary thrombosis. "For example, colony-stimulating factor 2 (CSF2) is a signaling chemokine that along with its cognate receptor pair CSF2RB modulates leukocyte production and proliferation as well as MSC recruitment and post-myocardial infarction (MI) cardiac remodeling." (PMID 37600026, 2023).
alveolar proteinosis (14 papers, 2007 to 2025). "Consistently, GM-CSF/CSF2 deficiency leads to alveolar proteinosis with enhanced susceptibility to respiratory infection." (PMID 30597969, 2018).
respiratory failure (14 papers, 2013 to 2025). The significant impairment of gas exchange within the lungs resulting in hypoxia, hypercarbia, or both, to the extent that organ tissue perfusion is severely compromised. "Taken together, CD11c-Cre/Ppargfl/fl mice with immature and dysfunctional AM show increased morbidity and respiratory failure due to an impaired removal of dead cells and debris following influenza virus infection similar to, but not as pronounced as Csf2−/− mice that are completely devoid of AM." (PMID 24699679, 2014).
liver fibrosis (13 papers, 2013 to 2025). "CSF2 is an important factor in the progression of liver fibrosis, and anti-CSF2 has been shown to ameliorate liver fibrosis." (PMID 35405942, 2022).
emphysema (12 papers, 2011 to 2025). "We predicted 39 molecular changes mostly related to inflammatory processes including known key emphysema drivers such as NF-κB and TLR4 signaling, and increased levels of TNF-α, CSF2, and several interleukins." (PMID 25962837, 2015). "Encouragingly, we verified various well-known mechanistic changes associated with emphysema development, such as NF-κB signaling and TLR4 signaling, as well as increased levels of TNF-α, CSF2, and non-predicted but related interleukins, MPO, and MMP-9 by means of proteomic analysis." (PMID 25962837, 2015).
coronary artery disease (10 papers, 2014 to 2024). "We also measured the plasma CSF2 levels in patients with stable coronary artery disease (non-MI participants) and patients who successfully underwent percutaneous coronary intervention operations (reperfusion therapy) after acute MI (MI/R patients)." (PMID 37064880, 2023).
head and neck squamous cell carcinoma (10 papers, 2011 to 2024). A squamous cell carcinoma that arises from any of the following anatomic sites: lip and oral cavity, nasal cavity, paranasal sinuses, pharynx, larynx, and salivary glands. "Another example would be the upregulation of CD24 in microglial cells and MMP-2 in head and neck squamous cell carcinoma by granulocyte-macrophage colony stimulating factor (CSF2)." (PMID 21359202, 2011).
skin carcinoma (10 papers, 2016 to 2022). "In skin cancers, CSF2 could regulate VEGFR secretion and recruit tumor-associated macrophages to perform its anti-proliferative ability." (PMID 31894857, 2020). "The role of CSF2 (GM-CSF) in skin cancer is context-dependent." (PMID 31051015, 2016).
endothelial dysfunction (9 papers, 2011 to 2024). In vascular diseases, endothelial dysfunction is a systemic pathological state of the endothelium (the inner lining of blood vessels) and can be broadly defined as an imbalance between vasodilating and vasoconstricting substances produced by (or acting on) the endothelium. "The “anti‐endothelial dysfunction (anti‐ED)” list consists of 31 genes that significantly ameliorate the ED phenotypes, with JUNB, NR4A3, SALL4, CSF2 and HEY1 being the top hits." (PMID 38031960, 2023).
Hypertension (9 papers, 2021 to 2025). The presence of chronic increased pressure in the systemic arterial system. "In addition, the s-CSF2-Ab levels were associated with intima-media thickness and hypertension." (PMID 36844744, 2023). "Moreover, the multivariate logistic regression analysis demonstrated that age, hypertension, and s-CSF2-Ab level were independent predictors of AIS." (PMID 36844744, 2023). "Furthermore, using multivariate logistic regression analysis, we identified age, hypertension, and s-CSF2-Ab as independent predictors of AIS." (PMID 36844744, 2023). "Significantly higher s-CSF2-Ab levels were observed in patients with hypertension than in those without hypertension (P = 0.020)." (PMID 36844744, 2023). "The s-CSF2-Ab levels were correlated well with hypertension and weakly with BP but were not correlated with glycated hemoglobin and blood glucose, which are typical DM markers." (PMID 36844744, 2023).
Insulin resistance (9 papers, 2011 to 2023). Increased resistance towards insulin, that is, diminished effectiveness of insulin in reducing blood glucose levels. "Csf2−/− mice fed with low fat, high fat or high fat cholesterol diets exhibited protection from diet induced insulin resistance when compared with wild type mice." (PMID 30065264, 2018). "Despite comparable adiposity, Csf2−/− mice were protected from HF diet induced glucose intolerance and insulin resistance when compared to Csf2+/+ and dietary supplementation of cholesterol had no additional effect." (PMID 30065264, 2018). "The metabolic health (as measured by body weight, adiposity, plasma fasting glucose, insulin, triglycerides, phospholipids, total cholesterol levels, and glucose and insulin tolerance tests) deteriorated with diet for both genotypes, while mice lacking Csf2 were protected from insulin resistance." (PMID 30065264, 2018).
ischemia (9 papers, 2011 to 2024). A hypoperfusion of the BLOOD through an organ or tissue caused by a PATHOLOGIC CONSTRICTION or obstruction of its BLOOD VESSELS, or an absence of BLOOD CIRCULATION. "Csf2 also abrogates ischemia and thus prevents cardiomyocyte death by neovascularization." (PMID 23335977, 2013).
small cell lung carcinoma (9 papers, 2018 to 2024). Small cell lung cancer (SCLC) is a highly aggressive malignant neoplasm, accounting for 10-15% of lung cancer cases, characterized byrapid growth, and early metastasis. "Previous studies have demonstrated that the phosphorylation of STAT3/MYC by CSF2 regulates the phenotypic plasticity of small cell lung cancer." (PMID 38817867, 2024). "With respect to anoikis resistance, a recent study in small-cell lung cancer reported that adherent cells express significantly more CSF2 than subclones of the same cell line that can survive in suspension." (PMID 38271085, 2024).
Candida infection (8 papers, 2009 to 2024). "For example, IL-17 stimulates the expression of Csf2 (encoding granulocyte-macrophage colony-stimulating factor (GM-CSF)) in NK cells to foster the differentiation and proliferation of Kupffer cells, thus endowing this cell subset with competence to control systemic candidiasis." (PMID 31337278, 2019). "GM-CSF is another cytokine that can be regulated by IL-23, as it has also been shown to be the case during systemic candidiasis However, when analyzing Csf2-/- mice, we could not gain evidence for the requirement of GM-CSF in promoting myeloid cell survival in the kidney of C. albicans-infected." (PMID 31887131, 2019).
endometriosis (8 papers, 2017 to 2024). The growth of functional endometrial tissue in anatomic sites outside the uterine body. "We previously showed that CSF-2, aka GM-CSF, was elevated in plasma of women with endometriosis and decreased after surgery for this disease and both CSF-2 and IL12 have been shown to be elevated in peritoneal fluid as well as endometrial and endometriotic cells of women with endometriosis." (PMID 38999962, 2024).
lung adenocarcinoma (8 papers, 2014 to 2025). A carcinoma that arises from the lung and is characterized by the presence of malignant glandular epithelial cells. "Additionally, researchers revealed that cancer-associated fibroblasts (CAFs) from osimertinib-resistant lung adenocarcinoma (LUAD) tissues produce higher levels of colony-stimulating factor 2 (CSF2) compared to those from osimertinib-sensitive tissues." (PMID 41425254, 2025).
periodontal disease (8 papers, 2017 to 2025). "Of these, colony-stimulating factor receptor 3 (CSFR3) was found to be involved in periodontal diseases; thereby, the colony-stimulating factor 2, which is originating from the same superfamily, contributed to the regulation of inflammatory response during periodontal homeostasis." (PMID 34925639, 2021).
renal carcinoma (8 papers, 2014 to 2025). A carcinoma arising from the epithelium of the renal parenchyma or the renal pelvis. "In parallel, CSF2-treated neutrophils significantly reduced intracellular ROS levels in co-cultured renal cancer cells, indicating a shift toward a less oxidative, pro-survival microenvironment." (PMID 41216204, 2025). "The protein levels of PD-L1 are significantly increased, while the levels of TRAIL and Bv8 are significantly decreased in renal cancer cells co-cultured with CSF2-treated neutrophils compared to the control group (P < 0.001)." (PMID 41216204, 2025). "In vitro, CSF2 promoted neutrophil polarization toward the tumor-supportive N2 phenotype and enhanced the proliferation and migration of renal cancer cells while inhibiting apoptosis and reactive oxygen species production." (PMID 41216204, 2025). "The number of migrated renal cancer cells in co-culture with CSF2-treated neutrophils is significantly higher than in the control group, and this migration-promoting effect is significantly reversed by 3-MA but not by CQ (P < 0.001)." (PMID 41216204, 2025). "The apoptosis rate of renal cancer cells co-cultured with CSF2-treated neutrophils is significantly lower than in the control group (P < 0.001)." (PMID 41216204, 2025). "In summary, this study confirmed that CSF2 induces N2 phenotype neutrophil polarization via the PD-L1 pathway, providing a new target and experimental basis for developing renal cancer therapies, which has significant clinical implications." (PMID 41216204, 2025). "The number of migrated renal cancer cells in co-culture with CSF2-treated neutrophils is significantly higher than in the control group (P < 0.001)." (PMID 41216204, 2025). "The level of ROS in renal cancer cells co-cultured with CSF2-treated neutrophils is significantly lower than in the control group (P < 0.001)." (PMID 41216204, 2025). "The apoptosis rate of renal cancer cells co-cultured with CSF2-treated neutrophils is significantly lower than in the control group, but this effect is partially reversed by 3-MA (P < 0.001)." (PMID 41216204, 2025). "The proliferation rate of renal cancer cells co-cultured with CSF2-treated neutrophils is significantly higher over 5 days compared to the control group (P < 0.001)." (PMID 41216204, 2025). "CSF2-treated neutrophils upregulate PD-L1 and suppress apoptosis-angiogenesis signaling in renal cancer cells." (PMID 41216204, 2025). "This further supports the role of CSF2-induced neutrophils in creating a pro-survival microenvironment for renal cancer cells, possibly by secreting anti-apoptotic cytokines or modulating cell signaling pathways." (PMID 41216204, 2025). "Structural modeling of CSF2–CSF2R and PD-L1–autophagy protein interactions could greatly accelerate therapeutic design targeting the CSF2–PD-L1 axis in renal cancer." (PMID 41216204, 2025). "This study hypothesizes that CSF2 facilitates renal cancer progression through the polarization of neutrophils toward the tumor-promoting N2 phenotype." (PMID 41216204, 2025). "when neutrophils were co-cultured with PD-L1 knockout renal cancer cells, the CSF2-induced shift toward the N2 phenotype was partially attenuated, with decreased CD163/CD206 expression and a partial recovery of CD54/CD86 levels compared to co-culture with wild-type tumor cells." (PMID 41216204, 2025). "Despite these findings, the specific role of CSF2 in modulating neutrophil polarization within the renal cancer microenvironment remains unclear." (PMID 41216204, 2025). "Flow cytometry and Western blot analyses revealed that CSF2-treated neutrophils upregulated PD-L1 expression and downregulated TRAIL and Bv8 in co-cultured renal cancer cells (P < 0.001)." (PMID 41216204, 2025).
renal carcinoma (continued). "Importantly, when co-cultured with PD-L1 knockout renal cancer cells, both N2 marker induction and ROS suppression were partially reversed, suggesting that tumor-derived PD-L1 is required for the full execution of the CSF2-induced immunosuppressive program in neutrophils." (PMID 41216204, 2025). "Western blot analysis demonstrated that CSF2 treatment increased autophagy-related proteins LC-3 II/I, ATG7, and Beclin1 in co-cultured renal cancer cells (P < 0.001)." (PMID 41216204, 2025).
ulcer (7 papers, 2013 to 2025). "Gene analysis results confirmed that expression changes occurred in genes of key regulators of wound healing, such as chemokines, MMP-1, 9, CSF-2, and IL-33, and that such genetic changes enhanced wound healing in ulcers." (PMID 37508509, 2023).
lymph node metastasis (6 papers, 2016 to 2026). "Patients with lymph node metastasis (N1 stage) exhibited significantly higher CSF2 expression than those without nodal involvement (N0 stage), indicating a potential role for CSF2 in facilitating lymphatic dissemination." (PMID 41216204, 2025).
prostate tumor (6 papers, 2015 to 2025). "According to Smartapp database analysis, multiple probes (cg17566874, cg13259290, cg08686879) were used in the CSF2 promoter region of BCa tissue in prostate tumor tissue β." (PMID 38817867, 2024).
cutaneous leishmaniasis (5 papers, 2012 to 2023). Leishmaniasis affecting the skin. "From the results of DisGeNET, the hub genes IL10, IL6, CXCL8, CSF2, IFNG, IL1B, and TNF were causing Visceral Leishmaniasis; IL10, IL4, CXCL8, IFNG, IL1B and TNF found to cause Cutaneous Leishmaniasis and Urban Cutaneous Leishmaniasis." (PMID 36989283, 2023).
E. coli infection (5 papers, 2020 to 2025). "However, concentration-dependent effects were observed: in E. coli infection, IL6 was upregulated in E1 while CSF2 (granulocyte-macrophage colony-stimulating factor) was upregulated in E3." (PMID 40771952, 2025).